BCL2 (BCL2 apoptosis regulator)
Diseases named in the same sentence as BCL2 in open-access papers (continued):
Sharing a sentence is not in itself a finding about the gene and the disease.
lymphoma (continued). "Since by definition, DH/TH lymphomas require the identification of MYC rearrangement, this should be explored first, followed by BCL2 and BCL6 gene study." (PMID 39684922, 2024). "New IHC quantification rules and the joint training with other immunohistochemical biomarkers, such as CD3, CD20, CD5, BCL2, BCL6, Ki67, and MUM1, would be valuable to provide more insights into diagnosis and treatment determination of lymphoma patients." (PMID 38538739, 2024). "BCL2 rearrangements were detected in 20 of 37 MYC rearranged cases (54%), and these “double-hit” lymphomas are described in the next paragraph." (PMID 38903717, 2024). "It represents 80–90% of DH/TH lymphoma cases, and it characterized by structural chromosomal aberrations with breakpoints at both MYC and BCL2 loci." (PMID 39684922, 2024). "These lymphomas predominantly belong to the germinal center B‐cell (GCB) subtype and exhibit strong expression of IRF4/MUM1 protein but lack the BCL2 gene translocation." (PMID 39415926, 2024). "A double-hit lymphoma is a high-grade B-cell lymphoma (HGBCL) with MYC and BCL2/BCL6 rearrangements." (PMID 39449881, 2024). "It has been reported that rituximab induces apoptosis in lymphoma cells by inhibiting various antiapoptotic constitutively activated signaling pathways, such as NF-κB, p38 MAPK, ERK1/2, AKT, Bcl-2, and Bcl-xL." (PMID 36691066, 2023). "Fluorescence in situ hybridization studies for MYC and BCL2 and/or BCL6 rearrangements were performed in 27 patients, and only one patient had double‐hit lymphoma." (PMID 37997571, 2023). "Bcl-2 overexpression has been implicated in several forms of cancer cells that rely heavily on Bcl-2 for their survival, such as chronic lymphocytic leukemia (CLL), certain types of lymphomas, and AML." (PMID 37685874, 2023). "There were two cases of FL (Cases LYWS-1099 and LYWS-1133), one grade 3A with BCL2 and IRF4 rearrangements, and one transformed FL to high-grade lymphoma that in the transformation acquired MYC and IRF4 rearrangements." (PMID 37555980, 2023). "No marked differences in the other BCL-2 family proteins examined (BCL-XL, BCL-2, MCL-1, BIM) were observed between lymphomas of the two genotypes." (PMID 37567974, 2023). "These lymphoma lines were treated in culture with a range of concentrations of the BH3-mimetic drugs S63845 (MCL-1 inhibitor) and ABT-737 (inhibitor of BCL-2 + BCL-XL + BCL-W)." (PMID 37567974, 2023). "Double-hit or Triple-hit lymphoma (DHL/THL) is an uncommon subset of B cell non-Hodgkin lymphoma with recurrent translocations involving MYC/8q24 and BCL2/18q21 and/or BCL6/3q27, according to the 2016 updated WHO classification of lymphoid neoplasias." (PMID 36823603, 2023). "BCL2, MYC, and/or BCL6 are simultaneously rearranged in so-called double-hit and triple-hit lymphomas, respectively." (PMID 37371852, 2023). "These mice also developed marginal zone lymphomas which harbor recurrent translocations between the Immunoglobulin loci and critical oncogenes including C-MYC, BCL2 and BCL644." (PMID 37160922, 2023). "Immunohistochemical results for lymphoma cells of left cervical lymph nodes were as follows: BCL6 (+), MUM1 (+), Ki-67 (80%+), CD20 (+), Pax5 (+), BCL2 (+), CD10 (+), CyclinD1 (-), and sparsely positive for CD3, CD5, CD15, CD30, CD68, and C-MYC." (PMID 38143763, 2023). "Nonetheless, all the peripheral blood samples in this study were acquired before 2022, and we still considered the DLBCL with MYC and BCL2 and/or BCL6 rearrangement as DHL/THL according to the 2016 World Health Organization classification of lymphoma." (PMID 36823603, 2023). "For instance, in lymphoma, LINK-A lncRNA was proved to overcome ibrutinib resistance through Akt/Bcl2 pathway." (PMID 36734243, 2023).
lymphoma (continued). "The percentage of patients with high-grade lymphoma with gene rearrangements in MYC and BCL2, BCL6, or both was similar." (PMID 37760639, 2023). "Double/triple-hit lymphomas (DHLs/THLs) are an aggressive type of high-grade B-cell lymphomas (HGBLs), characterized by translocations in MYC and BCL2/BCL6." (PMID 37958379, 2023). "As these DEL classifications do not take DLBCL ITH into account, it was not known if DELs represent two distinct and coexisting clonal phenotypes within a lymphoma—one expressing MYC and the other BCL2." (PMID 37071673, 2023). "For patients who were diagnosed with DLBCL or BL, MYC, BCL2, and BCL6 rearrangements should be detected by FISH to exclude double/triple-hit lymphoma." (PMID 37182167, 2023). "The rapid diagnosis of double/triple-hit lymphomas (DHLs/THLs) involving MYC, BCL2 and/or BCL6 rearrangements is obligatory for optimal patient care." (PMID 37958379, 2023). "Once confirmation of a hematolymphoid origin is established with CD45, the ideal IHC lymphoma work up for DLBCL includes CD3, CD20, CD5, CD10, bcl-2, bcl-6, MUM1, cyclin D1, CD30, Ki-67, and Epstein-Barr virus-encoded RNA (EBER) ISH." (PMID 37958219, 2023). "So-called double-hit lymphomas usually carry BCL2 and MYC rearrangements, while triple-hit lymphomas additionally bear BCL6-fusions." (PMID 37371852, 2023). "Specifically, SuperDendrix finds associations between increased dependency on the transcription factor TCF3 and the mutually exclusive set {myeloma, BCL2(A)} and the transcription factor IRF4 and {myeloma, lymphoma}." (PMID 35382456, 2022). "These lymphomas are known as double-hit (DH) or triple-hit (TH) lymphomas and, in the 2017 WHO classification, they belong to the provisional category of High-grade B-cell lymphomas with MYC and BCL2 or BCL6 rearrangements, or both (HGBCL-DH/TH)." (PMID 35200580, 2022). "The 5th edition of the WHO classification of haemato-lymphoid tumors 2022 acknowledges these similarity relations between the lymphoma entities and segregates DH BCL6 as a subtype of DLBCL, NOS or HGBL, NOS apart from the DH BCL2." (PMID 35884496, 2022). "FBXO10 and FBXO11 bind to BCL2 and BCL6, respectively, resulting in their ubiquitination and promoting their degradation, thereby regulating the levels of BCL2 and BCL6 proteins in lymphoma cells." (PMID 36644760, 2022). "Characterisation of Eμ-Myc/dCas9a-SAMKI/+/sgBcl-2 lymphomas revealed a B cell phenotype (CD19/B220 double positive) and high BCL-2 expression, which are both also observed in human DHL21." (PMID 35961968, 2022). "Although patients with DH lymphomas showed inferior PFS and OS when treated with R-CHOP, the prognostic impact of MYC and BCL2 (over)expression in DLBCL in DE lymphomas and HGBL-NOS is still not clear." (PMID 35326604, 2022). "The World Health Organization (WHO) classification considers cases with concurrent MYC and BCL2 and/or BCL6 rearrangement determined by fluorescence in situ hybridization (FISH) as “double-hit” lymphomas (DHL) or “triple-hit” lymphomas (THL), respectively." (PMID 35198451, 2022). "Combinatory treatment with Prexasertib and Venetoclax synergistically induced apoptosis as demonstrated by time-dependent increase in caspase 3/7 cleavage in BCL-2 positive ABC and DH lymphoma cell lines." (PMID 34304248, 2022). "Rapid and aggressive lymphomas develop that are characterised by CD19/B220 double positive tumour cells and the expression of high levels of both c-MYC and BCL-2, which are all markers of human DHL21." (PMID 35961968, 2022). "Triple expressor lymphoma is a subgroup of non-Hodgkin's lymphomas that exhibits simultaneous overexpression of the MYC, BCL2, and BCL6 genes." (PMID 36505167, 2022). "In the most aggressive forms of lymphoma, MSI2 is overexpressed and cooperates with PRMT5 in maintaining c-MYC and BCL-2, which confers resistance to PRMT5 inhibition." (PMID 36167829, 2022).
lymphoma (continued). "A more simplified algorithmic approach was adopted by the Royal College of Pathologists (UK) as outlined in the 2015 lymphoma dataset, which recommends testing MYC and BCL2 by FISH." (PMID 35626243, 2022). "Venetoclax is a highly selective oral BCL-2 inhibitor that showed anticancer activity in BCL2-dependent leukemia and lymphoma cell lines and mouse xenograft models as well as in primary cells, both as a single agent and in combination." (PMID 35884618, 2022). "Lymphomas with chromosomal rearrangements of MYC and BCL2 and/or BCL6 (double- and triple-hit lymphoma, now classified as high-grade lymphoma) are commonly of GCB subtype." (PMID 35305092, 2022). "The second strategy utilizes dual targeting of PRMT5 and BCL-2, using GSK-591 and venetoclax, that exhibits potent anti-tumor efficacy and induction of apoptosis across a wide range of lymphomas." (PMID 36167829, 2022). "In summary, our study provides data for the role of the PRMT5/MSI2 axis in regulating the key lymphoma drivers, c-MYC and BCL-2." (PMID 36167829, 2022). "Lymphoma material was analyzed regarding COO subtype, MYC, BCL2 and BCL6 expression (by IHC), as well as translocation status (by FISH)." (PMID 35326604, 2022). "The same study reported that the BFL-1 knockdown in lymphoma cells was insensitive to pharmacological inhibition of BCL-XL and BCL-2." (PMID 35201512, 2022). "Similar results have also been found in lymphomas and prostate cancer, where low apoptotic rates have been detected related to overexpression of RUNX2 and genes such as Myc and BCL2." (PMID 36510562, 2022). "High‐grade B‐cell lymphomas with MYC and BCL2 and/or BCL6 rearrangements were rare in the NPS, which is clinically relevant because these lymphomas have a poor prognosis." (PMID 35104916, 2022). "These so-called “double-hit” or “triple-hit” (DH/TH) lymphomas have been included in the 2016 updated WHO classification in the new category of high-grade B cell lymphoma (HGBL) with rearrangements of MYC and BCL2 and/or BCL6." (PMID 35060000, 2022). "Chromosomal translocations juxtaposing the oncogenes MYC, BCL2, or BCL6 and one of the immunoglobulin loci are hallmarks in the genesis of lymphomas." (PMID 35060000, 2022). "Those notions are especially significant since NF-kB, STAT3, PI3K, and AKT pathways are activated in lymphoma cells via leptin/LEPR signaling and improving bcl-2 expression." (PMID 36555171, 2022). "Therefore, to inhibit the PRMT5/MSI2/c-MYC/BCL-2 axis we proposed two drug combination strategies; the first one consists of targeting PRMT5 in combination with a MSI2 inhibitor, which results in loss of c-MYC and BCL-2 translation cell-cycle regulators in lymphoma cells." (PMID 36167829, 2022). "Double-hit lymphoma is one of the most aggressive and refractory lymphoma subtypes with recurrent genetic abnormalities of MYC and BCL-2 or BCL6 rearrangement, leading to a poor prognosis in the present clinical practice." (PMID 35091546, 2022). "These lymphomas are highly sensitive to treatment with venetoclax, the BH3-mimetic drug that specifically binds and inhibits pro-survival BCL-2." (PMID 35961968, 2022). "Subtyping of the lymphomas using CD20, CD10, Bcl2, and MUM1 revealed a total of 27/99 (27%) germinal center B‐cell (GCB) and 73/99 (74%) non‐GCB lymphomas according to the Hans classifier." (PMID 36051079, 2022). "“Double-hit” (with MYC, BCL2, or BCL6 alterations) and “triple-hit” (with MYC, BCL2, and BCL6 alterations) lymphomas are also aggressive in nature, and are part of the high-grade B-cell lymphomas." (PMID 34947882, 2021). "This is essential since double-hit lymphomas with aberrant expression of MYC and BCL2 has dismal outcome." (PMID 33737576, 2021).
lymphoma (continued). "Targeting BCL-2 with BH3 mimetics, such as ABT-199 (venetoclax), shows superior effects on lymphoma, especially when combined with homoharringtonine (HHT)." (PMID 34336680, 2021). "Li and colleagues tested BETi action on MYC activity and found that in both MYC/BCL2 DHL and MYC/BCL2/BCL6, triple-hit lymphoma cells were responsive to BETi (JQ1, I-BET, OTX) treatment." (PMID 33801599, 2021). "Double- and triple-hit lymphomas are now defined as “high-grade B-cell lymphoma (HGBCL) with rearrangements of MYC and BCL2 and/or BCL6”, an entity separate from DLBCL in the 2016 revision of the World Health Organization lymphoma classification." (PMID 34945817, 2021). "Patient 1 had a double-hit lymphoma with a MYC translocation and an additional BCL6 translocation and patient 5 had a triple hit lymphoma with additional BCL2 and BCL6 translocations." (PMID 33561953, 2021). "A similar phenomenon was observed here in the PCAWG lymphoma cohort, with SNV clustering at both promoter one (P1) and promoter two (P2) of BCL2, involving 44 lymphoma cases and 936 SNVs." (PMID 33554123, 2021). "The presence of rearrangements in all three of the genes (MYC, BCL2 and BCL6) characterizes a further subgroup of high-grade lymphomas called triple-hit lymphoma." (PMID 34943410, 2021). "At initial diagnosis, 70% of patients had Ann Arbor stage III/IV disease, 56% had non‐germinal center B‐cell‐like type DLBCL, and 42% had double‐expressor lymphoma (MYC and BCL2 expression)." (PMID 34105893, 2021). "These mice develop lymphomas with late or post-GC origin ABC-DLBCL phenotype, with an actionable dependence on BCL2." (PMID 34207773, 2021). "For the 1–2 kb upstream region, significant genes in the PCAWG cohort with a very high density of SNVs included BCL2 and long non-coding RNA LINC01136, primarily involving lymphoma cases." (PMID 33554123, 2021). "Sixty-four (45.4%) tumors showed a MYC rearrangement; 29 (20.57%) samples thereof had an additional BCL2 rearrangement (hence belonging to the DHL category); one lymphoma sample revealed translocations in MYC, BCL2, and BCL6 (THL)." (PMID 34830747, 2021). "In fact, poor clinical outcomes for lymphomas patients with co-expression of MYC and BCL2 were previously reported." (PMID 33718209, 2021). "Triple‐hit lymphoma (THL), which is classified into high‐grade B‐cell lymphoma with rearrangements of MYC, BCL2 and BCL6, presents aggressive biological behaviour." (PMID 34698437, 2021). "It was soon recognized that BCL2 was involved in the regulation of apoptosis and that it cooperated with the MYC oncogene in lymphoma pathogenesis." (PMID 34576319, 2021). "Immunophenotyping and molecular studies, performed later, established a diagnosis of de novo B-cell precursor leukemia/lymphoma with MYC, BCL2 rearrangements (Double-hit lymphoma)." (PMID 34307232, 2021). "In the most recent WHO review of lymphoma classification, the DHL/THL category is now recognized as "high-grade B-cell lymphoma (HGBL) with rearrangements of MYC and Bcl-2 and/or Bcl-6." (PMID 33412518, 2021). "Patients with ABC-DLBCL or genetic alterations in MYC and BCL2 and/or BCL6, called double hit (DHL) or triple hit lymphomas (THL), generally have a poor survival prognosis." (PMID 35008680, 2021). "Regarding the baseline characteristics of the lymphomas, 70.8% of the tumors expressed MUM1, 65.2% expressed BCL2, and 72.7% expressed BCL6." (PMID 34782660, 2021). "Notable genes with SNV-associated increased expression include TERT, COPS3, POLE2 and HDAC2—involving multiple cancer types—MYC, BCL2, PIM1 and IGLL5—involving lymphomas—and CYHR1—involving pediatric low-grade gliomas." (PMID 33554123, 2021).
lymphoma (continued). "Other two subtypes represented by Double-Hit Lymphomas (DHL) (5–10% of all DLBCL lymphomas) and Double-Expressor Lymphomas (DEL), present MYC and BCL2 protein overexpression, together with the GCB and ABC subtypes." (PMID 33216822, 2020). "HGBLs harboring MYC and BCL2 or BCL6 translocation, commonly known as double-hit (DH) lymphoma, are frequently refractory to therapy, leading to early relapse and poor patient prognosis." (PMID 33182440, 2020). "These malignancies are also known as double-hit (MYC/BCL2 or MYC/BCL6 translocations) and triple-hit (MYC/BCL2/BCL6 translocations) lymphomas (DHL/THL), and represent 5–10% of DLBCL patients." (PMID 33260693, 2020). "Immunohistochemistry showed positivity for Ki-67 (approximately 90%), BCL2 (approximately 80%) and MYC (approximately 70%) double-expressor lymphoma." (PMID 32664092, 2020). "In the 2017 WHO lymphoma classification, MYC/BCL6-DH DLBCL are included in the double-hit category, without any distinction from those with MYC/BCL2/BCL6-TH or MYC/BCL2-DH." (PMID 31844144, 2020). "The results described here establish a clinically relevant mouse model of double-expressor lymphoma by targeting constitutive expression of c-MYC and BCL2." (PMID 32695674, 2020). "We evaluated this in the lymphoid cancer cell lines RS4;11 and GRANTA-519, both of which express high levels of NOXA and are sensitive to the BCL2 inhibitor ABT-199." (PMID 32094511, 2020). "Our study identifies a unique set of cases that have concurrent translocations and copy number gains in MYC, BCL2, and/or BCL6 outside of DH/TH lymphoma that cannot readily be identified using standard FISH alone." (PMID 33168821, 2020). "Diffuse large B cell (DLBCL) and high grade B cell lymphomas (HGBL) demonstrating MYC translocation with concurrent BCL2 and/or BCL6 rearrangements, colloquially called double and triple hit lymphomas (DHL and THL), have poor clinical outcomes." (PMID 31932576, 2020). "The 2016 WHO classification recognizes and categorizes high‐grade B‐cell lymphomas (HGBCL) with MYC and BCL2 and/or BCL6 gene rearrangements as a separate entity, commonly referred to as “double‐hit” lymphomas." (PMID 31659781, 2020). "IHC analysis also helps define the double expressor DLBCL (c-MYC/BCL-2 overexpression, 25% of de-novo DLBCL cases), while FISH determines the double/triple hit lymphomas (genetic rearrangement of c-MYC/BCL-2 or BCL-6, 6-14% of de-novo DLBCL cases)." (PMID 32019190, 2020). "As regards DH lymphomas, MYC and BCL2 rearrangements frequently trigger the corresponding protein overexpression, characterizing a specific group called DPE lymphomas, clinically featuring rapid progression and poor outcome." (PMID 31940809, 2020). "Immunohistochemical studies confirmed that all lymphomas expressed BCL6, CD10, and CD23, and most expressed variable BCL2." (PMID 32555149, 2020). "While translocations in MYC, BCL2, and BCL6 represent significant genomic events in lymphoma, less is known about the contribution of chromosomal copy number alterations (CNAs) in these genes to existing translocations." (PMID 33168821, 2020). "In comparison, the reference HDAC inhibitor, SAHA, only marginally reduced the expression of the poor prognostic factors of MYC, BCL-2, and BCL-6 in the tested lymphoma cell lines." (PMID 32575557, 2020). "In comparison, BCL-2 and BFL-1/A1 mRNA levels were highest in leukemia/lymphoma and melanoma cell lines." (PMID 32131385, 2020). "Double/triple hit lymphoma (DH/TH), known as high-grade B-cell lymphoma (HGBL), is an aggressive diffuse large B cell lymphoma (DLBCL), defined as having concurrent MYC, BCL2, and/or BCL6 gene rearrangements." (PMID 33168821, 2020). "Patients with lymphoma cells co-expressing MYC and BCL-2 have been shown to respond better to ABT-737 (a selective inhibitor of BCL-2, BCLxL, and BCLw), showing that BCL-2 has a critical role in DHL." (PMID 33216822, 2020).